MFSD11 (major facilitator superfamily domain containing 11)
Synonyms: ET; FLJ22196; FLJ20226
Tractability: Antibody: UniProt predicts a signal peptide or a membrane-spanning region.
Gene: Protein-coding gene on chromosome 17 (76,735,865 to 76,781,449, forward strand). Ensembl gene ENSG00000092931.
Subcellular location: Membrane
Gene Ontology:
Molecular function: protein binding
Cellular component: membrane
Genetic constraint (gnomAD): Loss-of-function variants: 25 observed, 36.56 expected, observed/expected ratio (o/e) 0.68, 90% interval 0.5 to 0.95. The upper end of that interval is the gene's LOEUF score, 0.95, which puts it in group 4 of 6, group 1 being the genes least tolerant of losing a copy. Missense variants: 438 observed, 468.31 expected, observed/expected ratio (o/e) 0.94, 90% interval 0.86 to 1.01. Synonymous variants: 167 observed, 163.82 expected, observed/expected ratio (o/e) 1.02, 90% interval 0.9 to 1.16.
Homologues: Orthologues: chimpanzee MFSD11 (100% identical), macaque MFSD11 (99% identical), dog MFSD11 (96% identical), pig MFSD11 (95% identical), guinea pig MFSD11 (95% identical), rat Mfsd11 (93% identical), mouse Mfsd11 (93% identical), rabbit MFSD11 (92% identical), tropical clawed frog mfsd11 (67% identical), zebrafish mfsd11 (49% identical), Drosophila melanogaster CG18549 (41% identical), Caenorhabditis elegans C27C12.4 (31% identical), and 16 more.
Diseases named in the same sentence as MFSD11 in open-access papers:
MFSD11 is named in the same sentence as 4 diseases in open-access papers, as found by Europe PMC text mining. Sharing a sentence is not in itself a finding about the gene and the disease. The quoted sentences say what the papers report.
Intellectual disability (1 paper, 2020). "Recently, MFSD11 was identified as a novel candidate linked to intellectual disability." (PMID 32733888, 2020).
mental disorder (1 paper, 2022). A disease that has its basis in the disruption of mental process. "Eight genes are implicated in viral (SEC14L1, JMJD6, SRSF2, TMPRSS2, MX1, MX2) or bacterial (COL8A1, SPIRE1) infections, seven genes (MFSD11, METTL23, CTTNBP2, BACE2, IMPA2, MPPE1 and GNAL) are involved in mental disorders and one gene (MGAT5B) is related to the Golgi complex." (PMID 35581286, 2022).
neurological disorders (1 paper, 2022). "Indeed, identified genes are implicated in viral (SEC14L1, JMJD6, SRSF2, TMPRSS2, MX1, MX2) bacterial (COL8A1, SPIRE1), and neurological disorders (MFSD11, METTL23, CTTNBP2, BACE2, IMPA2, MPPE1 and GNAL), or in the functions of the Golgi complex (MGAT5B), organelle where viral envelope is occurred." (PMID 35581286, 2022).
MFSD11 also shares sentences with these, for which no sentence is quoted: neurodegenerative disease (1 paper).